NRAS (NRAS proto-oncogene, GTPase)
Diseases named in the same sentence as NRAS in open-access papers (continued):
Sharing a sentence is not in itself a finding about the gene and the disease.
melanoma (continued). "A panel of patient‐derived melanoma cell lines with confirmed NRAS mutations were collected to study the combination effect of the RAF dimer inhibitor, brimarafenib, with the MEKi, mirdametinib." (PMID 41199020, 2025). "Other studies also confirm a lower rate of BRAF and NRAS mutations in spitzoid melanoma compared to other melanoma subtypes." (PMID 39415471, 2025). "Previous research suggests that many lesions diagnosed as an SM or AST, that developed distant metastases and resulted in a fatal outcome, were actually conventional melanomas harboring BRAF or NRAS mutations, frequently accompanied by TERT-p alterations." (PMID 40227833, 2025). "In particular, NRAS gene mutations occur in 20–30% of melanomas and rarely coexist with BRAF V600E, appearing together in 1% of cases only." (PMID 40868208, 2025). "Mucosal melanoma patients carrying NRAS mutations demonstrated a remarkable response rate to the combination therapy of atezolizumab and bevacizumab." (PMID 39757723, 2025). "This study demonstrates the efficacy of this combination in NRAS‐mutated melanoma and is currently also investigated in a phase I/IIa clinical study." (PMID 41199020, 2025). "For patients with NRAS-mutated melanoma, binimetinib as a single agent can be offered to patients who do not benefit from prior anti-PD-1 therapy [III, C]." (PMID 39550033, 2025). "Targeting the CD133/AKT/survival pathways with capivasertib, together with the MEKi trametinib, underscores the potential for combinatorial therapies for the development of more effective treatments for melanoma patients with difficult-to-treat NRAS mutations." (PMID 39996721, 2025). "Melanoma cells derived from two PDXs harboring NRAS (MM13) or BRAF (MM27) mutations were engineered to express H2B-GFP via lentiviral transduction." (PMID 40528051, 2025). "Numerous research efforts are currently focused on developing targeted therapies for melanomas driven by NRAS mutations, NF1 loss-of-function mutations, and other genetic alterations that activate the MAP kinase pathway." (PMID 40867277, 2025). "Another member of the MAPK pathway, the GTPase NRAS, is observed to be mutated in about 30% of all melanoma cases, with the most common mutations in either exon 1 (G12 or G13) or exon 2 (Q61)." (PMID 41199020, 2025). "In vitro studies have also provided encouraging perspectives: for example, the combination of vemurafenib and binimetinib amplifies pro-apoptotic activity in melanoma with NRAS mutation." (PMID 40141318, 2025). "Somatic mutations in the oncogenes BRAF and NRAS result in activation of the intracellular mitogen-activated protein kinase (MAPK) pathway that is involved in melanoma pathogenesis." (PMID 40867317, 2025). "Accordingly, it has been recently shown that NRAS-mutated melanomas have lower PRDX2 (peroxiredoxin 2) expression compared to BRAF-mutated melanomas, which is correlated with lower survival and higher malignancy in patients." (PMID 40141318, 2025). "Key findings include the potential therapeutic value of FTIs for NRAS-mutated melanoma and GNAQ/GNA11-mutated uveal melanoma by inhibiting INPP5A farnesylation." (PMID 39995872, 2025). "Here we combined the H2B-GFP label-retention system and a surface marker approach to isolate and extensively characterize in vitro and in vivo quiescent cells in our NRAS or BRAF mutated human melanoma PDXs." (PMID 40528051, 2025). "Targeting MEK is currently the most developed targeted strategy in NRAS-mutated melanoma while KIT inhibitors are approved for KIT-mutated cases specifically." (PMID 40331942, 2025). "The NRAS‐mutation pathway is another pathway of melanoma, leading to MAPK pathway activation, and mutations are generally found in Q60/61 and G12/13 codons." (PMID 40761498, 2025). "NRAS mutations are present in approximately 11% of all cancers and are commonly found in 15% of melanomas." (PMID 40362630, 2025).
melanoma (continued). "NRAS mutations typically develop during the initial formation of melanoma and are preserved throughout its pathogenesis." (PMID 39940799, 2025). "Neuroblastoma RAS viral oncogene homolog (NRAS) mutations occur in 15–20% of melanomas and are associated with aggressive behavior and poor prognosis." (PMID 40508177, 2025). "First-line immunotherapy options for patients with NRAS-mutated melanoma are identical to those for patients with NRAS-WT disease [I, A]." (PMID 39550033, 2025). "We describe the case of a patient with a history of CLL on surveillance who was subsequently found to have recurrent Stage IIIC melanoma who appeared to test positive for both an NRAS G12D and a BRAF V600E mutation." (PMID 39940799, 2025). "In NRAS‐mutated melanoma cell lines, mirdametinib treatment led to increased MEK phosphorylation, though ERK phosphorylation was reduced in a dose‐dependent manner." (PMID 41199020, 2025). "In this study, plasma-derived levels of ctDNA from assays for BRAF and NRAS driver mutations as well as TERT promotor mutations were analyzed in patients with advanced melanoma." (PMID 40002300, 2025). "Firstly, the homogeneous disorganized pattern was directly significantly associated with NRAS-mutated melanoma, whereas the multicomponent pattern was inversely associated with NRAS-mutated melanoma." (PMID 40867317, 2025). "BRAF mutation was more frequently observed in ulcerated melanoma (16/23; 69.6%), with mitotic rate ≥ 5 n/mm2 (8/11; 72.7%), while NRAS mutation was more common in amelanotic/hypomelanotic (8/17; 70.0%) and nodular melanoma (10/24; 41.7%)." (PMID 40867317, 2025). "In vivo studies further validated these findings, showing that the combination treatment inhibited tumor growth and significantly prolonged survival in mouse models bearing patient‐derived NRAS‐mutated melanoma tumors." (PMID 41199020, 2025). "Secondary mutations in NRAS, observed in 20%–30% of resistant cases, enable melanoma cells to bypass BRAF blockade by reactivating the MAPK/ERK signaling cascade, facilitating continued cell proliferation." (PMID 39897423, 2025). "One of the key challenges in developing effective targeted therapies is the lack of preclinical models that accurately recapitulate the tumor microenvironment (TME) and the intrinsic resistance of melanoma cells bearing NRAS mutations." (PMID 41035005, 2025). "In vitro, the brimarafenib and mirdametinib combination exhibited synergistic effects, significantly inhibiting the growth of patient‐derived NRAS‐mutated melanoma cell lines." (PMID 41199020, 2025). "Genetic mutations, such as those in the BRAF and NRAS genes, are implicated in melanoma pathogenesis." (PMID 41394861, 2025). "DNA NGS testing at our institution revealed a BRAF wild-type, NRAS G12D-mutation-positive melanoma consistent with his original molecular report, prior to the melanoma." (PMID 39940799, 2025). "Incidentally, the amplification of a mutated NRAS gene has been reported also by Dr. de la Fouchardiere’s group in an adult who developed malignant melanoma arising in a trichroblastoma." (PMID 39810001, 2025). "Dermoscopically, shiny white structures (OR = 3.50; 95% confidence interval: 1.13–10.84) were associated with BRAF-mutated melanomas, whereas a homogeneous disorganized pattern was associated with NRAS-mutated melanomas (OR = 6.96; 1.49–32.53)." (PMID 40867317, 2025). "In melanoma with BRAF/NRAS mutations, PRKN is downregulated, while BRAFV600E or MAPK inhibition can increase PRKN expression leading to cytostatic and apoptotic effects." (PMID 40862737, 2025). "With this approach, we successfully transdifferentiated BRAF-mutated (A375, HT144, MA1) and NRAS-mutated human melanoma cells (SKMel30, SKMel103) as well as murine Ret melanoma cells derived from Ret transgenic mice." (PMID 40715046, 2025). "Patients with NRAS‐mutated melanoma generally have poorer outcomes, with a higher likelihood of brain metastases." (PMID 41199020, 2025).
melanoma (continued). "Previous studies involving NRAS-mutant melanoma focused on targeting the mutational sites of point-mutated oncogenic NRAS-mRNA21,22." (PMID 40473796, 2025). "Given the tolerability of this combination in vivo, our results suggest that brimarafenib and mirdametinib represent a promising therapeutic strategy for patients with NRAS‐mutated melanomas and potentially other RAS‐mutated solid tumors." (PMID 41199020, 2025). "NRAS mutations are prevalent in human hematological malignancies and are also common in certain solid tumors, including melanoma and colon cancer." (PMID 40091521, 2025). "BRAF mutations are most commonly associated with superficial spreading melanoma and tumors located on the trunk, whereas NRAS mutations correlate with nodular melanoma and extremity localization." (PMID 41007741, 2025). "On the genetic side, mutations in genes such as BRAF and NRAS have been implicated in the pathogenesis of melanoma." (PMID 39777336, 2024). "Despite the aggressiveness linked to this alteration, other studies showed a similar or better response to immunotherapy in patients carrying the NRAS mutated tumors compared to NRAS wildtype melanomas." (PMID 39148899, 2024). "In the context of NRAS-mutant melanoma, the resistance to MEK inhibition was also associated with the persistent formation of the active eIF4F complex." (PMID 39436655, 2024). "The overall survival of patients with BRAF-positive mutant melanoma has improved significantly since the discovery of targeted therapy, although the prognosis of NRAS-mutated patients tends to be far poorer." (PMID 38127894, 2024). "Disulfiram and its metabolite diethyldithiocarbamate are known to have antitumor effects related to cellular stress, and induction of endoplasmic reticulum (ER) stress was found to synergize with MEK inhibitors in NRAS-mutated melanoma cells." (PMID 38263136, 2024). "This is reminiscent of our previous project, in which BRAF inhibitors acted as potent ER stress inducers in NRAS-mutated melanoma cells to increase apoptosis rates after MEK inhibition." (PMID 38263136, 2024). "In this regard, the detection of a NRAS mutation at position 61 in one of our cases represents a pitfall as this genotype is noted in 20—40% of melanomas, the frequency varying with the clinicopathological tumor type." (PMID 39196362, 2024). "Nevertheless, in stage 4 melanoma, NRAS mutation serves as an independent predictor, indicating shorter survival." (PMID 38891988, 2024). "NRAS is the most frequently mutated RAS isoform in melanoma and many hematologic malignancies, with a prevalence of approximately 20% to 40% in acute myeloid leukemia (AML), myelodysplastic syndrome (MDS) and juvenile chronic myelomonocytic leukemias." (PMID 38317235, 2024). "For example, NRAS-mutated melanoma cells reprogram a quiescent metabolic program to avoid MEK-inhibition-induced cell apoptosis with increased reactive oxygen species (ROS) levels, making these cells highly sensitive to ROS induction." (PMID 38732242, 2024). "This retrospective study indicates that advanced melanoma with NRAS mutations exhibits better immune-based treatment outcomes than non-NRAS mutations." (PMID 39195270, 2024). "Next-generation sequencing (NGS) studies suggest a potential association between TRPM6 and NRAS-driven melanoma, but the specific mechanism remains to be clarified." (PMID 39633507, 2024). "NRAS also stands out as a relevant driver of melanoma since its mutations are detected in approximately 20% of all cases." (PMID 38790974, 2024). "NRAS mutations, which are found in 15–20% of melanoma cases, are significant drivers of the disease, affecting melanoma development through a distinct pathway." (PMID 38474231, 2024). "c-KIT mutations, while less common than BRAF and NRAS mutations, play a significant role in certain melanoma subtypes, particularly mucosal and acral melanomas." (PMID 38474231, 2024).
melanoma (continued). "Using the same ddPCR technology (Bio-Rad Laboratories, Hercules, CA, USA), an NRAS Q61 mutation was found in malignant peripheral nerve sheath tumors that were further identified as melanoma." (PMID 38396984, 2024). "Of these, the most common are the BRAF and NRAS oncogenes, with 50% of melanomas demonstrating the BRAF mutation (BRAFV600E)." (PMID 38275910, 2024). "UV-induced mutations in the BRAF and NRAS genes are also significant risk factors in melanoma development." (PMID 38534742, 2024). "Similar to other mucosal melanomas, c-KIT, BRAF, and NRAS mutations are frequently detected in female genital melanomas." (PMID 38988710, 2024). "NRAS mutations have been described in about 15-20% of melanoma patients, mutually exclusive with BRAF mutations, except in rare cases." (PMID 39148899, 2024). "Current evidence reveals prominent PI3K/AKT signaling in NRAS G12 mutant cells and augmented MAPK signaling in NRAS Q61 variants, suggesting that NRAS G12 and NRAS Q61-mutant melanoma tumors differ in biology." (PMID 38396984, 2024). "We demonstrate that eIF4F is essential for controlling ERK signaling intensity in treatment-naïve melanoma cells harboring BRAF or NRAS mutations." (PMID 39436655, 2024). "The identification of NRAS mutations is not only essential for understanding melanoma’s genetic diversity, but also plays an important role in clinical decision-making, particularly in cases without BRAF mutations." (PMID 38474231, 2024). "When combined, SHP2 seems to have an oncogenic function in melanoma and presents a viable new target for melanoma combination treatment, which includes tumors with NRAS and BRAF mutations." (PMID 38504984, 2024). "In any case, we expected ERK signaling in melanoma cells bearing NRAS mutations to be highly sensitive to RocA." (PMID 39436655, 2024). "The results strongly supported the notion that eIF4F negatively controls ERK signaling and eIF4Fi-induced ERK hyperactivation stimulates the EGR1 promoter activity in both BRAF- and NRAS-mutated melanoma cells." (PMID 39436655, 2024). "Forty-six existing tissue samples (34 out of 46 were BRAF/NRAS mutated) of metastatic malignant melanoma from 21 patients that originate from diagnostic testing undertaken at the Klinikum Kassel from January 2015 to September 2022 were analysed." (PMID 38127894, 2024). "Most patients had either BRAFV600E/K (40%) or NRAS (30%) mutation-positive melanoma, and half of the patients received pembrolizumab." (PMID 38280045, 2024). "mRNA vaccines intricately target genes such as BRAF and NRAS mutations to provoke robust immune responses against melanoma-associated antigens." (PMID 39582535, 2024). "Nodular melanoma and melanomas resulting from persistent UV exposure on the skin frequently have NRAS mutations." (PMID 38534309, 2024). "In patients with advanced NRAS-mutated melanoma previously treated with immune checkpoint inhibitors, the preliminary overall response rate was 38% with bocodepsin and binimetinib compared historically to 16% for binimetinib alone in the NEMO trial." (PMID 38429789, 2024). "While the frequency of NRAS mutation in the included studies was seemingly higher than in the general melanoma population, as reported in previous literature, this was not statistically significant due to the limited data available." (PMID 38765703, 2024). "Despite the infrequency of BRAF mutations in this melanoma type, genotyping for both NRAS and BRAF is recommended as a result of the effectiveness of available inhibitors." (PMID 39202970, 2024). "Mutational screening revealed the coexistence of BRAF and NRAS mutations in melanomas and nevi and the occurrence of NRAS G12/G13 variants in healthy skin." (PMID 38396984, 2024). "Though NF1 mutations are typically seen in melanomas that lack mutations in BRAF or NRAS, nearly 4% of melanomas with mutations in BRAF or NRAS also harbor NF1 mutations." (PMID 38247727, 2024).
melanoma (continued). "NRAS is mutated in 15–20% of melanoma patients, leading to persistent downstream activation of the ERK pathway, resulting in uncontrolled cell growth and migration." (PMID 39633507, 2024). "We demonstrate that eIF4F is essential for maintaining optimal ERK signaling intensity in treatment-naïve melanoma cells harboring BRAF or NRAS mutations." (PMID 39436655, 2024). "The development of NRAS Q16R IHC provides an accurate, rapid, and cost-effective method for detecting the presence of an NRAS Q61R mutation in melanomas." (PMID 38247727, 2024). "In contrast to KRAS mutations which are most frequently in codon 12, the most common NRAS mutations in melanomas occur at codon 61 (Q61R or Q61K)." (PMID 39379700, 2024). "In our set of melanoma samples, encompassing 11 specimens positive for NRAS mutations, we performed a statistical analysis to investigate potential correlations between NRAS mutational status and the clinicopathological variables of the tumors." (PMID 38396984, 2024). "It was revealed that NRAS mutation is more frequent in melanomas arising within congenital melanocytic nevi." (PMID 39473498, 2024). "Up to 95% of giant CN are found to have an NRAS mutation and most melanomas arising in giant CN also exhibit NRAS mutations." (PMID 38247727, 2024). "Immunotherapy with programmed cell death protein checkpoint inhibitors, such as nivolumab or pembrolizumab, is the first line of treatment for surgically incurable stage III/IV melanoma with NRAS mutations." (PMID 38462618, 2024). "Mutation in the BRAF and NRAS accounts for 50 and 30 % of the total cause of melanoma, respectively." (PMID 38560710, 2024). "So far, targeted therapies specifically addressing NRAS-mutated melanoma have shown limited success." (PMID 38474231, 2024). "Prognostically, compared with the BRAF-mutated NRAS wild-type melanomas, the NRAS-mutated melanomas have been related to more aggressive biological behavior with a higher risk of distant metastasis." (PMID 38247727, 2024). "In contrast, NRAS mutations, although less common, are linked to shorter survival times in stage IV melanoma." (PMID 38474231, 2024). "The phase 3 NEMO trial evaluated binimetinib, another MEKi, versus dacarbazine chemotherapy in patients with advanced NRAS-mutated melanoma." (PMID 38263136, 2024). "The development of more effective treatment options for NRAS-mutated melanoma is a key objective of current clinical investigations, reflecting the continuous effort to improve therapeutic outcomes for this challenging subset of melanoma patients." (PMID 38474231, 2024). "Mutations in the BRAF gene occur in ~40–85% of melanoma cases, with the lowest frequency in primary melanomas, increased in metastatic sites, and the highest in recurrent melanomas, while NRAS mutation occurs in ~25%." (PMID 39766280, 2024). "The exploration of NRAS mutations and genomic subtypes enhances the understanding of melanoma heterogeneity, guiding the implementation of multigene ctDNA mutation detection for refined prognostication." (PMID 38539531, 2024). "Among these mutations, BRAF and NRAS are two of the most common, but also mutually exclusive mutated oncogenes recognised in melanoma." (PMID 39766280, 2024). "Truncating mutations in this gene activate its oncogenic potential and lead to increased proliferation of NRAS-mutated melanoma cells by activating the PI3K/AKT pathway and RAC1." (PMID 39340537, 2024). "In our small batch of melanoma samples, NRAS mutational status exhibited correlations with two of the most important histological predictors of clinical outcome: Breslow thickness (p = 0.01) and the mitotic index (p = 0.04)." (PMID 38396984, 2024).